LGI1 (leucine rich glioma inactivated 1)
Diseases named in the same sentence as LGI1 in open-access papers (continued):
Sharing a sentence is not in itself a finding about the gene and the disease.
psychosis (16 papers, 2016 to 2025). "The past few years have shown growing evidence of acute onset psychosis in children that is immune-mediated, particularly with N-Methyl-D-Aspartate (NMDA) receptor, Leucine-rich glioma inactivated-1 (LGI-1), contactin-associated protein-like 2 (CASPR2), and Glutamic Acid Decarboxylase (GAD65)." (PMID 39286808, 2024). "We tested serum from SLE psychosis patients for an array of antibodies directed against neuronal cell surface antigens that have been implicated as targets in psychosis (GABABR, DPPX, AMPAR1/2, NMDAR, LGI1, CASPR2) in order to try and identify potential biomarkers." (PMID 33629101, 2021). "Here, we describe a man aged 58 years with no psychiatric history who developed a severe and acute psychotic disorder following resolution of a protracted course of limbic encephalitis associated with antibodies to leucine-rich glioma inactivated 1 protein." (PMID 28363946, 2017). "NMDAR, LGI1 and GABA-A antibodies were found more prevalent in people with psychosis than in healthy controls." (PMID 31174586, 2019). "The presence of NMDAR, of leucine-rich, glioma inactivated 1 (LGI1) and of gamma-aminobutyric acid type A (GABA-A) receptor antibodies in patients with a first episode of psychosis was found to be greater then in healthy controls." (PMID 31174586, 2019). "The absence of a distinctive metabolomic profile in those with NMDAR/LGI1/CASPR2 serum antibodies in psychosis does not necessarily indicate that these antibodies are not having an effect in the brain in these patients." (PMID 36131046, 2022). "By contrast, likely non-immune syndromes were noted in only one patient with LGI1 antibodies (stroke) and in four with CASPR2 antibodies (axonal neuropathy, cervical dystonia, hemifacial spasm and psychosis)." (PMID 29788256, 2018). "Similarly, in a cohort of patients with first-episode psychosis PANSS scores, cognitive testing and catatonia symptoms were not clinically significant different in anti-neuronal antibody positive (NMDAR, CASPR2, LGI1 or GABAA receptor antibodies) and negative patients." (PMID 30390633, 2018).
amnesia (15 papers, 2015 to 2025). Pathologic partial or complete loss of the ability to recall past experiences ( AMNESIA, RETROGRADE) or to form new memories ( AMNESIA, ANTEROGRADE). "Prominent amnesia is a hallmark of limbic encephalitis associated with LGI1-antibodies; autobiographical memory is particularly impaired, often with significant confusion and disorientation." (PMID 32873782, 2020). "Frequent focal seizures and amnesia are the two hallmarks of LGI1 and CASPR2 antibody-related central nervous system (CNS) diseases." (PMID 29055902, 2018). "Malvaso and colleagues reported that patients with LGI1- or CASPR2-associated limbic encephalitis may present with isolated disturbances of memory, particularly marked retrograde amnesia, and that cognitive recovery in such cases is often incomplete." (PMID 41488641, 2025). "One striking clinical hallmark in patients with autoantibodies to leucine-rich glioma inactivated 1 (LGI1) is the very frequent focal seizure semiologies, including faciobrachial dystonic seizures (FBDS), in addition to the amnesia." (PMID 38662480, 2024). "Patients with LGI1-antibody and NMDAR-antibody syndromes, and other forms of limbic encephalitis, often experience a dense amnesia for the period of acute hospitalisation, especially the nadir of their disease." (PMID 34108243, 2021). "Limbic dysfunction, such as temporal seizures, anterograde amnesia or hyperintensities in the MRI are uncommon in Morvan’s syndrome, except in patients who are both CASPR2 and LGI1-antibody positive." (PMID 32873782, 2020).
hippocampal atrophy (15 papers, 2017 to 2025). "Additionally, brain MRI can reveal hippocampal atrophy in several AE, especially in LGI1-Ab patients both early in the disease course and in almost all patients during follow-up." (PMID 40274643, 2025). "Autoantibodies directed against Leucine-rich Glioma-Inactivated protein 1 (LGI1) are found in patients with limbic encephalitis (LE) who have frequent focal seizures and hippocampal atrophy as hallmarks of their disease." (PMID 36078121, 2022). "Encephalitis in patients positive for VGKC-complex, LGI1, or CASPR2 antibodies can present with inflammatory changes of the medial temporal lobe on acute MRI, and whole-hippocampal atrophy in the convalescent and chronic phases." (PMID 28369215, 2017). "In both cases, associated with anti-LGI1 and anti-NMDAR, no hippocampal atrophy was observed as previously reported." (PMID 31139134, 2019). "Furthermore, unlike anti-LGI1, hippocampal atrophy/sclerosis is not generally seen on long-term follow-up, however, supratentorial white matter blurring has been reported, again at a lower rate." (PMID 38327544, 2024).
sleep disorder (15 papers, 2018 to 2025). A change from the patient's baseline sleeping pattern, in the hours slept and/or an alteration/dysfunction in the stages of sleep. "Anti-leucine-rich glioma-inactivated 1 limbic encephalitis (anti-LGI1 LE) is a rare type of autoimmune LE with a unique presentation, comprising neuropsychiatric disturbances, sleep disorders, and faciobrachial dystonic seizures (FBDS)." (PMID 39664290, 2024). "Although insomnia has not been widely documented in anti-LGI1 LE, a study from France described a 65-year-old patient with this condition who presented with reversible sleep disturbances." (PMID 40271344, 2025).
myasthenia gravis (14 papers, 2016 to 2026). Myasthenia gravis (MG) is a rare, clinically heterogeneous, autoimmune disorder of the neuromuscular junction characterized by fatigable weakness of voluntary muscles. "IgG4-mediated syndromes (e.g., LGI1, IgLON5), Myasthenia Gravis." (PMID 41562781, 2026). "Thymoma is the classic association for myasthenia gravis (AChR antibodies) but is also strongly linked to central nervous system (CNS) syndromes such as Morvan syndrome and limbic encephalitis (LE), mediated by anti-CASPR2, anti-LGI1, and anti-CRMP5 antibodies." (PMID 41562781, 2026). "However, in this case, limbic encephalitis with concomitant LGI-1 antibodies and typical faciobrachiodystonic seizures was diagnosed without evidence of cancer, malignant thymoma, signs of myasthenia gravis or additional clinical phenotypes." (PMID 38438516, 2024).
dementia (13 papers, 2019 to 2025). Loss of intellectual abilities interfering with an individual's social and occupational functions. "For instance, in a large AE cohort more than one-third of patients with LGI1-, CASPR2-, N-methyl-D-aspartate receptor (NMDAR)- or GABABR-Abs fulfilled diagnostic criteria for dementia." (PMID 40274643, 2025). "The frequencies followed a similar pattern compared to Candida-specific T cells, being more frequent in young controls compared to aged controls and dementia patients (NMDAR > mGluR5 > LGI1)." (PMID 40537813, 2025). "This case raises the awareness that a rapid progressive dementia with predominant memory deficits could be induced by immunoreactions against LGI1." (PMID 30732585, 2019). "In a recent study, NSAbs (GlyR, GABAAR, LGI1, CASPR2, and GABABR) were detected in 13.8% (n = 13) of patients with dementia and parkinsonism, mostly presenting with unclassified forms of disorders and in 2% (n = 1) of healthy individuals." (PMID 36101827, 2022).
cognitive decline (12 papers, 2014 to 2026). "We discuss a patient who presented to the emergency department (ED) with progressive cognitive decline, seizures, memory loss, and emotional instability who was ultimately diagnosed with anti-LGI-1 antibody LE." (PMID 34437034, 2021). "LGI1-AE commonly affects middle-aged and older adults, has a male predisposition and presents with seizures and cognitive decline." (PMID 34975832, 2021). "Clinical features of anti-LGI1 LE include various types of seizures, slow progressive cognitive decline, and psychiatric abnormalities." (PMID 40007925, 2025). "The present case was diagnosed as anti-LGI1 LE, with possible facio-brachial dystonic seizures, epileptic seizures, and slowly progressive cognitive decline." (PMID 40007925, 2025). "Patient LE#2 had a series of complex partial seizures and a history of cognitive decline and was classified as LGI1-LE." (PMID 36672216, 2023). "Here, we report a case of anti-LGI1 antibody-positive LE presenting with focal impaired awareness seizures, non-convulsive status epilepticus, and tonic-clonic seizures, alongside slowly progressive cognitive decline." (PMID 40007925, 2025).
Parkinsonism (12 papers, 2018 to 2025). Characteristic neurologic anomaly resulting from degeneration of dopamine-generating cells in the substantia nigra, a region of the midbrain, characterized clinically by shaking, rigidity, slowness of movement and difficulty with walking and gait. "Nonetheless, several case reports and case series accurately illustrate LGI1-Ab patients with parkinsonism, chorea, and myoclonus, reporting misdiagnosis as MSA or PSP and even an initial suspicion of Huntington’s disease." (PMID 40274643, 2025). "We herein report a 67-year-old patient with positive LGI1 antibody titers, who developed subacute parkinsonism after serial COVID-19 vaccination." (PMID 41311428, 2025). "Given the possible association with COVID-19 vaccination, an autoimmune encephalopathy panel was sent, confirming positive LGI1 antibodies and leading to a diagnosis of LGI1 encephalitis with parkinsonism." (PMID 41311428, 2025). "One retrospective study (2013–2021) from South India included 23 patients with LGI1 antibodies who showed progressive slowness, gait disturbances, and paroxysmal episodes of falls resembling Parkinsonism." (PMID 41311428, 2025). "Several studies have also shown that patients with LGI1 autoantibody disease exhibited Parkinsonism symptoms." (PMID 35964138, 2022). "▪ Movement disorders such as chorea, dyskinesias, dystonias, or myoclonus (associated with multiple antibodies including anti- NMDAR, CASPR2, LGI1,Ri, Hu, or CV2/CRMP5); and rarely parkinsonism (associated with anti-Ri, NMDAR, LGI1, and D2R)." (PMID 33935958, 2021). "Moreover, increasing evidence indicates a strong association between RBD and Parkinson’s disease, dementia with Lewy bodies (DLB), and voltage-gated potassium channel antibody-associated limbic encephalitis, principally against CASPR2 and LGI1." (PMID 35382765, 2022). "Patients with LGI1, IgLON5, DPPX and GABABR antibodies have been misdiagnosed with Parkinson’s disease (PD), progressive supranuclear palsy (PSP), cortico-basal syndrome (CBS) or multisystem atrophy (MSA)." (PMID 36979644, 2023). "However, non-paraneoplastic encephalitides also can manifest with parkinsonism: indeed, patients with LGI1, DPPX and GAD antibodies have been misdiagnosed with Parkinson’s disease, PSP or multisystem atrophy." (PMID 29053777, 2018).
temporal lobe epilepsy (10 papers, 2010 to 2025). A localization-related (focal) form of epilepsy characterized by recurrent seizures that arise from foci within the temporal lobe, most commonly from its mesial aspect. "ADLTE is characterized by heritable temporal lobe epilepsy with auditory ictal manifestations; mutations in the leucine-rich glioma-inactivated 1 (LGI1) gene at the 10q24 locus were identified through linkage analysis." (PMID 40217881, 2025). "LGI1 mutations were also associated to temporal lobe epilepsy with aphasic seizures, demonstrating that other ictal manifestations are to be considered in the phenotypic spectrum of temporal lobe epilepsy with auditory features." (PMID 35153984, 2021). "Interestingly, the clinical presentation is often similar to genetic disorders with mutations in the same target protein (e.g. focal seizures in LGI1-Abs (leucine rich glioma inactivated 1) and familial temporal lobe epilepsy with mutation in the LGI1 gene." (PMID 33324898, 2019). "Both PEPS and ADLTE are temporal lobe epilepsies and LGI1 and LGI2 are closely related paralogues that share the same functional domains." (PMID 20863412, 2010). "LGI1 is the best studied gene of the LGI family and it is responsible for causing autosomal dominant lateral temporal epilepsy (ADLTE) or autosomal dominant partial epilepsy with auditory features (ADPEAF), one type of familial temporal lobe epilepsy." (PMID 20863412, 2010). "A laboratory‐based cohort of LGI1‐IgG‐positive patients and control cohorts, including patients with mixed non‐inflammatory disorders (MNID), Alzheimer's disease (AD), and temporal lobe epilepsy (TLE) were analyzed." (PMID 40781580, 2025).
Chorea (9 papers, 2018 to 2025). Chorea (Greek for 'dance') refers to widespread arrhythmic involuntary movements of a forcible, jerky and restless fashion. "Anti-leucine-rich, glioma inactivated-1 (LGI-1) antibodies typically cause facio-brachial dystonic seizures, however chorea has also been reported." (PMID 35136702, 2022). "In one case report, a patient with LGI1 antibody syndrome with chorea responded to a 5-day course of 1000 mg methylprednisolone daily followed by a short taper." (PMID 32775036, 2020). "Among the nine patients with abnormal movements, five had chorea/dyskinesia (all had anti-NMDAr with one patient also presented with catatonia), two had faciobrachial dystonic seizures (both had anti-LGI1), one had stiff-person syndrome (anti-AMPAr-2), and one had myoclonus (anti-GABAr)." (PMID 31694559, 2019). "Finally, LGI1 or CASPR2 antibodies can also cause isolated or combined chorea/hemichorea, with or without neuropsychiatric symptoms, but typically without any underlying malignancy." (PMID 29053777, 2018). "Presentations of idiopathic autoimmune chorea with neuronal specific antibodies include GAD-65, LGI1, and CASPR2, although these antibodies are not specific for chorea and are associated with a myriad of other neurologic signs." (PMID 35370928, 2022). "LGI1 and CASPR2 antibodies are felt to be pathogenic, and are associated with well-described syndromes that typically do not include chorea." (PMID 35370928, 2022).
Alzheimer disease (8 papers, 2021 to 2025). A progressive, neurodegenerative disease characterized by loss of function and death of nerve cells in several areas of the brain leading to loss of cognitive function such as memory and language. "For example, patients with LGI1 autoantibodies can present to memory clinics with anterograde amnesia and behavioral abnormalities suggestive of Alzheimer’s disease (AD) or frontotemporal dementia (FTD)." (PMID 39050125, 2024). "A progressive anti-LGI1 encephalitis with isolated late-onset cognitive dysfunction has been described as a treatable imitator of Alzheimer’s disease (AD)." (PMID 38131803, 2023). "We present a case of anti-LGI1 LE who was initially misdiagnosed with Alzheimer disease because his clinical manifestations were similar to Alzheimer disease." (PMID 34398024, 2021).
Ataxia (8 papers, 2018 to 2025). Ataxia refers to impaired coordination of voluntary muscle movement. "Figures suggested that patients with AMPAR-Ab had the highest occurrence of cerebellar ataxia during the course of the disease (1/4, 25%), followed by CASPR2-Ab (2/12, 16.7%), NMDAR-Ab (9/108, 8.3%), and LGI1-Ab (2/52, 3.8%)." (PMID 35250990, 2022).
schizophrenia (8 papers, 2014 to 2025). A major psychotic disorder characterized by abnormalities in the perception or expression of reality. "Significantly, mutations in NgR1 have been associated with schizophrenia and we have recently identified mutations in NgR1 and LGI1 within schizophrenia patients that cause impairments in NgR1-LGI1-RhoA signaling." (PMID 30225353, 2018). "In this study, we analyzed two unrelated schizophrenia populations for mutations in LGI1 and RTN4R (NgR1)." (PMID 27468420, 2016). "Variants in NgR1 and LGI1 may be associated with schizophrenia and variants in NgR1 found in schizophrenic patients have impaired LGI1–NgR1 signaling." (PMID 27468420, 2016). "This is the first report of variants in LGI1 associated with schizophrenia." (PMID 27468420, 2016). "We report the first LGI1 mutations to be identified in individuals with schizophrenia." (PMID 27468420, 2016). "However, the identification of the previously reported R399W mutation in RTN4R and the existence of three distinct LGI1 mutations raise the possibility that these genes may be involved in schizophrenia pathogenesis." (PMID 27468420, 2016). "Impairments in synapse formation are common in neurological disease and we hypothesized that an LGI1–NgR1 signaling pathway may contribute to the development of schizophrenia." (PMID 27468420, 2016). "The screening of RTN4R and LGI1 genes did not indicate that these genes are common variants associated with schizophrenia." (PMID 27468420, 2016). "The gene leucine-rich glioma-inactivated 1 gene (LGI1) in autosomal dominant partial epilepsy with auditory features, may also play a role in regulating glutaminergic synaptic transmission, a process that is involved in the pathophysiology of schizophrenia." (PMID 24625201, 2014). "Other antibodies, including those against LGI1, GABABR, DPPX, AMPAR1/R2, and CASPR2, were absent from the CSFs of patients with schizophrenia." (PMID 38770306, 2024).
insomnia (7 papers, 2013 to 2025). A sleep disorder characterized by difficulty in falling asleep and/or remaining asleep. "In the literature, insomnia was reported to be more common in AIE associated with anti-NMDAR Ab, anti-CASPR2 Ab, and less frequently with anti-LGI1 Ab." (PMID 38913197, 2024).
COVID-19 (6 papers, 2022 to 2025). A disease caused by infection with severe acute respiratory syndrome coronavirus 2. "Testing of antibodies to several other autoantigens including CENP-A, PLA2R, and LGI1 that are found in patients with systemic sclerosis, membranous nephropathy, and limbic encephalitis, respectively, revealed little or no autoantibodies in any of COVID-19 adults (data not shown)." (PMID 35360001, 2022).
multiple sclerosis (6 papers, 2020 to 2026). A progressive autoimmune disorder affecting the central nervous system resulting in demyelination. "We also observed a shift of natural killer cells and loss of mucosa-associated invariant T (MAIT) cells in the CSF of LGI1-AIE and the blood of LGI1- and CASPR2-AIE compared with idiopathic intracranial hypertension and multiple sclerosis controls." (PMID 40094812, 2025). "In comparison to idiopathic intracranial hypertension and multiple sclerosis controls, we observed clonal CSF-specific antibody-secreting cell expansion in LGI1/CASPR2-AIE despite mostly normal CSF findings." (PMID 40094812, 2025). "We performed single-cell RNA sequencing of fresh CSF and parallel blood samples of 15 patients with LGI1-AIE (n = 9) and CASPR2-AIE (n = 6) compared with control patients [multiple sclerosis (n = 15) and idiopathic intracranial hypertension (n = 18)]." (PMID 40094812, 2025). "Therefore, we aimed at better characterizing the intrathecal and systemic immune compartment in LGI1- and CASPR2-AIE in comparison to idiopathic intracranial hypertension (IIH) and multiple sclerosis (MS) disease control patients." (PMID 40094812, 2025).